FAP (fibroblast activation protein alpha)
Diseases named in the same sentence as FAP in open-access papers (continued):
Sharing a sentence is not in itself a finding about the gene and the disease.
periodontitis (1 paper, 2025). An acute or chronic inflammatory process that affects the tissues that surround and support the teeth. "This study identified a positive genetic causal relationship between increased FAP expression and the risk of periodontitis." (PMID 39716898, 2025). "Accordingly, this study identified a positive association between FAP levels and periodontitis susceptibility using Mendelian randomization analysis." (PMID 39716898, 2025). "Hence, the increased proportion of FAP+ fibroblasts in periodontitis was strongly associated with oxidative stress–induced cellular senescence." (PMID 39716898, 2025). "Thus, inhibiting FAP activity alleviates bone loss and collagen degradation in periodontitis." (PMID 39716898, 2025). "Immunohistochemical analysis indicated a significant increase in FAP expression within the gingival connective tissue (lamina propria) of patients with periodontitis, accompanied by significantly decreased OLN expression." (PMID 39716898, 2025). "Human and mouse periodontitis tissues show elevated FAP and reduced osteolectin (OLN), an endogenous FAP inhibitor, indicating a FAP/OLN imbalance." (PMID 39716898, 2025). "Single‐cell RNA sequencing revealed gingival fibroblasts (GFs) as the primary FAP and OLN source, with periodontitis‐associated GFs showing increased reactive oxygen species, cellular senescence, and mTOR pathway activation." (PMID 39716898, 2025). "This study highlights FAP as a critical immune regulator in the pathogenesis of periodontitis and underscores its potential as a promising therapeutic target for periodontitis." (PMID 39716898, 2025). "Investigating the specific mechanisms by which FAP regulates macrophages in periodontitis is highly important and could provide valuable insights for therapeutic development." (PMID 39716898, 2025). "In conclusion, cellular senescence in gingival fibroblasts during periodontitis progression may play a critical role in the disruption of the balance of FAP and OLN expression." (PMID 39716898, 2025). "However, the significant increase in FAP+ fibroblasts is likely to delay bone repair in periodontitis." (PMID 39716898, 2025). "Since the pro‐inflammatory activation of macrophages and osteoclast differentiation are critical in periodontitis progression, FAP may play a role in macrophage activation during periodontitis." (PMID 39716898, 2025). "Finally, using a selective FAP small‐molecule inhibitor in vivo successfully alleviated periodontitis progression." (PMID 39716898, 2025). "Recombinant FAP increased pro‐inflammatory cytokine secretion and osteoclast differentiation in macrophages, exacerbating periodontal damage, whereas FAP inhibition reduced macrophage inflammation, collagen degradation, and bone resorption in experimental periodontitis." (PMID 39716898, 2025). "However, further studies are required to determine the optimal concentration and delivery route for FAP inhibitors in the treatment of periodontitis, along with large animal and clinical trials to validate their safety and therapeutic efficacy." (PMID 39716898, 2025). "However, regarding communication frequency, FAP+ fibroblasts exhibited markedly increased interactions with dendritic cells and macrophages, which was more pronounced in periodontitis." (PMID 39716898, 2025). "In summary, FAP contributes to periodontitis progression by promoting the pro‐inflammatory phenotype of macrophages and enhancing osteoclast differentiation, while FAP inhibition offers a promising strategy to mitigate alveolar bone resorption and inflammation in periodontitis." (PMID 39716898, 2025). "However, the role and mechanism of FAP in periodontitis remain unexplored." (PMID 39716898, 2025). "This study found a disruption in the balance between FAP and OLN in periodontitis, manifested by increased FAP and decreased OLN expression." (PMID 39716898, 2025).
periodontitis (continued). "The imbalance of fibroblast activation protein (FAP) and osteolection (OLN) in fibroblasts promotes the progression of periodontitis." (PMID 39716898, 2025). "Following the reclassification of these subgroups and analysis of their proportional changes, we observed a significant increase in FAP+ fibroblasts and a decrease in OLN+ fibroblasts in periodontitis samples." (PMID 39716898, 2025). "FAP and OLN expressions were significantly elevated and reduced, respectively, in fibroblasts from periodontitis patients." (PMID 39716898, 2025). "Consequently, targeting FAP may offer a promising therapeutic strategy for periodontitis." (PMID 39716898, 2025). "We found that disrupting the FAP and OLN balance contributes to the destruction of soft and hard tissues in periodontitis." (PMID 39716898, 2025). "Thus, FAP inhibition may represent a promising therapeutic strategy for periodontitis treatment." (PMID 39716898, 2025). "Overall, senescent gingival fibroblasts disrupt the FAP/OLN balance via the mTOR signaling pathway, playing a critical role in periodontitis progression." (PMID 39716898, 2025). "Therefore, FAP with endopeptidase activity may be involved in periodontitis progression." (PMID 39716898, 2025). "Therefore, senescent fibroblasts drive the FAP/OLN imbalance through mTOR activation, contributing to periodontitis progression." (PMID 39716898, 2025). "Notably, the correlation coefficient (R2) between FAP and OLN expression in fibroblasts decreased from 0.5 in healthy fibroblasts to 0.24 in periodontitis fibroblasts, suggesting a disrupted co‐expression pattern." (PMID 39716898, 2025). "Additionally, we observed a disruption in the balance of FAP and OLN expression in periodontitis tissues." (PMID 39716898, 2025). "Furthermore, the imbalance of FAP and OLN expression observed in periodontitis gingival tissues was mitigated following in vivo clearance of senescent cells using ABT263." (PMID 39716898, 2025). "Therefore, the balance between FAP and OLN is disrupted during periodontitis progression." (PMID 39716898, 2025).
polyposis (1 paper, 2021). "The clinical characteristics, including the age at first visit, sex, FAP classification, extra-intestinal manifestation, and the family history of patients with APC negative and APC mutant polyposis are summarized in SupplementaryTable S4." (PMID 33628596, 2021).
primary immunodeficiency (1 paper, 2024). "Similarly, genes associated with high FAP expression exhibited significant enrichment in Hematopoietic cell lineage and primary immunodeficiency." (PMID 39170615, 2024).
proliferative vitreoretinopathy (1 paper, 2023). Vitreoretinal membrane shrinkage or contraction secondary to the proliferation of primarily retinal pigment epithelial cells and glial cells, particularly fibrous astrocytes, followed by membrane formation. "Thus, it was found that the number of FAPα-positive cells correlates with the number of cells positive for SNAIL, CD44, HIC-5, and RAGE in the case of proliferative vitreoretinopathy." (PMID 38136590, 2023).
prostate disease (1 paper, 2022). "However, little is known about the cancer stage-specific expression patterns of FAP in prostate disease due to a small number of patients that already underwent FAPI-PET imaging." (PMID 34854061, 2022). "Although it seems interesting to track the long-term changes in this particular control patient, if it might progress into a cancerous lesion, this situation reflects the current uncertain prognostic value of FAP expression in early prostate disease." (PMID 34854061, 2022). "Further, persistent FAP expression in inflammatory environments such as BPH and prostatitis might offer options to observe and detect malign development in realtime and non-invasively." (PMID 34854061, 2022). "The expression of FAP in prostate disease settings, tumorous as well as inflammatory seems to not necessarily linked to cancer-associated fibroblasts but also expressed by benign myofibroblasts in suspected chronic prostate inflammation." (PMID 34854061, 2022).
radiation pneumonitis (1 paper, 2021). Inflammation of the lung due to harmful effects of ionizing or non-ionizing radiation. "Future studies could try to assess whether FAP-specific PET at baseline is better at predicting radiation pneumonitis than conventional pretreatment imaging." (PMID 33606104, 2021).
restrictive lung diseases (1 paper, 2025). "Pulmonary FAP expression has been shown to be elevated in restrictive lung diseases." (PMID 40542858, 2025).
Sepsis (1 paper, 2020). Sepsis is defined as life-threatening organ dysfunction caused by a dysregulated host response to infection. "This would provide us with the information whether the observed reduction in enzymatic activity in the most extreme form of sepsis develops gradually or at once and whether DPP4 and/or FAP should be used as a target to watch in patients with a high risk of developing sepsis." (PMID 32315321, 2020). "In a baboon model of sepsis, gene expression of FAP in the lung was maximal at 24 hours post E. coli challenge, probably reflecting the active tissue remodeling." (PMID 32315321, 2020). "Therefore, in the future, it would be very interesting to study larger groups of patients and to prospectively include all patients at high risk of developing sepsis and measure, for example, their DPP4- and FAP-activities on a daily basis." (PMID 32315321, 2020). "DPP4, FAP and PREP are good in discriminating between septic shock patients and ICU controls and should be further explored to see whether they are already dysregulated in earlier stages, opening perspectives for their further investigation as biomarkers in sepsis." (PMID 32315321, 2020).
skin inflammatory diseases (1 paper, 2024). "While CD74 is overexpressed in skin inflammatory diseases and Fibroblast Activation Protein (FAP) is overexpressed in cutaneous cancers, implying a potential role of these markers in disease pathogenesis, isolating cells based solely on a single marker remains impossible." (PMID 39056788, 2024).
squamous papilloma (1 paper, 2024). A benign epithelial neoplasm characterized by a papillary growth pattern and a proliferation of neoplastic squamous cells without morphologic evidence of malignancy. "Direct sequencing of the FAP amplicon obtained from the squamous papilloma DNA sample generated a partial L1 nt sequence shown to belong to BPV4 by BLASTn evaluation (99.32% identity; accession number: OP682875)." (PMID 39459892, 2024).
ST Elevation Myocardial Infarction (1 paper, 2023). A myocardial infarction that produces elevation in the ST segments of the ECG. "Also, another group measured FAPα concentration in plasma samples from patients with ST-elevation myocardial infarction (STEMI) and healthy donors." (PMID 37880678, 2023).
thoracic cancer (1 paper, 2025). A primary or metastatic malignant neoplasm affecting the tissues of the thorax. "This study is the first to analyze circulating FAP concentrations in patients with intra-thoracic cancer undergoing radiation therapy." (PMID 40690098, 2025).
tongue squamous cell carcinoma (1 paper, 2024). A squamous cell carcinoma that arises from the tongue. "Here, we observed that the culture supernatant derived from tongue squamous cell carcinoma Cal-27 cells could induce the activation of fibroblasts and lead to high expression of α-SMA, FAP, and PDGFR-β." (PMID 38169376, 2024). "CAFs and adjacent cancer fibroblasts were isolated from tongue squamous cell carcinoma and adjacent tissues, and both expressed vimentin but not keratin, while CAFs highly expressed α-SMA and FAP." (PMID 38169376, 2024).
tonsillar carcinoma (1 paper, 2025). "In contrast, [18F]F-FAPI-74-PET/CT demonstrated focal, intense FAP expression in the right palatine tonsil (green arrow), suggestive of a primary tonsillar carcinoma." (PMID 40647503, 2025). "Subsequent [18F]F-FAPI-74-PET/CT demonstrated focal FAP expression in the right palatine tonsil, raising suspicion of a tonsillar carcinoma, as well as increased FAPI uptake in correlation with postoperative changes following lymph node dissection." (PMID 40647503, 2025).
upper respiratory infection (1 paper, 2023). "Lately, a phase I clinical trial (NCT01722149) enrolled four patients with metastatic pleural mesothelioma (MPM) using FAP targeting CAR T-cells (CART-FAP) have been reported safe, with major SAEs including upper respiratory infection and thromboembolic event." (PMID 37784082, 2023).
tumor (1,426 papers, 2005 to 2026). "Stratification by GG in MRI‐visible tumours showed that both stromal and epithelial FAP were positively associated with increasing grade (Kruskal–Wallis test, p < 0.01), while stromal αSMA was enriched in lower‐grade tumours (p < 0.01)." (PMID 41410015, 2026). "Epithelial FAP and stromal αSMA showed additional prognostic associations in selected analyses, particularly in MRI‐visible tumours." (PMID 41410015, 2026). "Based on single-cell analysis revealing RNF157's heterogeneous expression in cancer-associated fibroblasts (CAFs) and tumor-associated macrophages (TAMs), we performed validation experiments using lentiviral shRNAs targeting FAP in CAFs and CD11b in TAMs." (PMID 41657776, 2026). "Fibroblast activation protein-targeted radionuclide therapy (FAP-TRT) has emerged as a novel strategy for modulating the tumour microenvironment (TME) by selectively eradicating FAP-expressing cancer-associated fibroblasts (CAFs)." (PMID 41622307, 2026). "Another promising target gaining interest is fibroblast activation protein (FAP), predominantly expressed on cancer-associated fibroblasts (CAFs) within the tumor microenvironment." (PMID 41510167, 2026). "This heterogeneous FAP distribution suggests the beginning of EMT in the tumor periphery, associated with possible ECM remodeling." (PMID 40694103, 2026). "Unlike in our earlier work, with the DL‐based compartment‐specific analysis we observed an association of poor BCR‐free survival with stromal FAP not only in MRI‐visible tumour regions but also in MRI‐invisible tumours." (PMID 41410015, 2026). "In summary, FAP is robustly overexpressed in MPNSTs at transcript and protein levels, potentially concentrates in high-risk tumor cell states, and is detectable by targeted PET imaging." (PMID 41591566, 2026). "FAP of the serine protease family is a significant indicator for detecting tumor-linked fibroblasts in most epithelial cancers." (PMID 41146237, 2025). "In an oncological context, FAP is mainly expressed in the tumor microenvironment (TME) on cancer associated fibroblasts (CAFs)." (PMID 41348275, 2025). "Another tumor-associated protein that has gained attention as a theragnostic target is the fibroblast activation protein (FAP), which is often expressed in the stroma of epithelial cancers and on tumor cells of EOC." (PMID 41466165, 2025). "Recently, a protocol using two markers, podoplanin (PDPN) and FAP, has been proposed for CAF identification; PDPN+ FAP− CAFs, as lymphoid tissue organizer phenotypes, identified the population that promotes and organizes tumor-associated TLS formation." (PMID 41154405, 2025). "Fibroblast activation protein (FAP) is highly expressed in the stroma surrounding tumours and is a specific surface marker for cancer-associated fibroblasts, which are the target of FAP inhibitor (FAPI) PET." (PMID 40637055, 2025). "A particularly robust and reproducible finding across studies in ccRCC and other epithelial tumors is the association between FAP expression and local tumor invasion." (PMID 41303595, 2025). "Fibroblast activation protein-α (FAP)-positive cancer-associated fibroblasts and macrophages represent potential targets for improving the tumor immunosuppressive microenvironment." (PMID 40328736, 2025). "Our analysis further unveiled that the co-occurrence of high percentages of FAP + CAFs, T-cyt, T-reg, and macrophages (above the P75 threshold) at the center of the primary tumor was significantly associated with worse CSS." (PMID 39751643, 2025). "At the invasion front of GC, increased tissue FAP is linked to poorer prognosis, lower tumor cell differentiation, higher TNM stage, and serosal invasion." (PMID 41244835, 2025). "In this study, FAP expression was associated with higher levels of clinical tumor markers, indicating a poorer prognosis." (PMID 41036616, 2025).